WIPF1 (WAS/WASL interacting protein family member 1)
Diseases named in the same sentence as WIPF1 in open-access papers (continued):
Sharing a sentence is not in itself a finding about the gene and the disease.
tumor (21 papers, 2016 to 2025). "In summary, BRAF V600E-activated MAP kinase pathway causes hypomethylation and overexpression of WIPF1; WIPF1 then functions like an oncoprotein to robustly promote aggressive cellular and tumor behaviors of PTC." (PMID 27863429, 2017). "It has also been shown that WIPF1 has oncogene characteristics and plays an important role in promoting tumor growth and metastasis." (PMID 40004503, 2025). "We found 38 cases with low expression and 139 with high expression of WIPF1 in the tumor tissues (cut-off value = 4.81; the partition was constructed by the length of OS)." (PMID 30041660, 2018). "Forced expression of WIPF1 stimulated the expression of YAP/TAZ and overcame the suppression of YAP/TAZ by miR-141/200c, consistent with a previous study that showed WIPF1 stimulated tumor growth by enhancing YAP/TAZ stability." (PMID 30041660, 2018). "Knockdown of WIPF1, as confirmed by the diminished protein and mRNA expression, reduced cell proliferation and tumor growth of primary site." (PMID 30041660, 2018). "We observed that knockdown of WIPF1 significantly decreased tumor growth both in volume and in the final tumor weight." (PMID 27863429, 2017). "Cox proportional regression model was used to identify a four-gene (WIPF1, PPIB, BASP1, PLOD2) signature that were significantly associated with overall survival (OS), and all the four genes were significantly upregulated in tumor tissues." (PMID 34257533, 2021). "WIPF1 was found to drive tumor progression by stabilizing the YAP/TAZ complex." (PMID 30041660, 2018). "Interestingly, our data showed the lack of inhibition on cell proliferation by miR-200c, despite both microRNAs displayed the inhibitory effect on tumor cell invasion, migration, metastasis as well as expression of WIPF1." (PMID 30041660, 2018). "Our data show that silencing of WIPF1 blocks tumor growth and metastasis while high expression of WIPF1 in human PDAC was associated with inferior patient survival, consistent with the previous study that high expression of WIPF1 was associated with poor survival in other types of malignancy." (PMID 30041660, 2018). "Results showed that the expression level of genes including MORF4L2, CTSL1, WIPF1, CXCL13, C5orf15, LIPA, and ISG20 significantly elevated in tumor tissues." (PMID 36639648, 2023). "Remarkably, silencing of WIPF1 blocked PDAC growth and metastasis both in vitro and in vivo, whereas forced WIPF1 overexpression antagonized the tumor suppressive effect of miR-141/200c." (PMID 30041660, 2018). "Remarkably, tumor vascular invasion could be observed in control tumors with intact BRAF and WIPF1, while, in contrast, no vascular invasion was observed in the tumors with WIPF1 or BRAF knockdown." (PMID 27863429, 2017).
WIPF1 also shares sentences with these, for which no sentence is quoted: glioblastoma (9 papers); glioma (9); immune deficiency (8); autoimmune disease (3); infection (3); actinopathies (2); anaplastic large cell lymphoma (2); breast tumor (2); primary immunodeficiencies (2); Autoimmunity (1); chronic obstructive pulmonary disease (1); combined immunodeficiency (1); Congenital thrombocytopenia (1); E. coli infection (1); hematological malignancies (1); hematopoietic cancers (1); infectious disease (1); lung adenocarcinoma (1); lymph node metastasis (1); lymphopenia (1); malignant glioma (1); Megakaryocytic leukemia (1); metastatic carcinoma (1); non-Hodgkin lymphoma (1); Opportunistic infection (1); pancreatic adenocarcinoma (1); peripheral nervous system diseases (1); platelet disorders (1); pulmonary arterial hypertension (1); T-cell deficiency (1).
A further 5 diseases each share a sentence with WIPF1 in 1 paper.